STIM2 (stromal interaction molecule 2)
Diseases named in the same sentence as STIM2 in open-access papers (continued):
Sharing a sentence is not in itself a finding about the gene and the disease.
lymphoproliferative disorder (1 paper, 2024). "Mice deficient in both Stim1 and Stim2 in T cells develop a lymphoproliferative disorder with markedly increased number of splenic TFH cells and diminished TFR cells in secondary lymphoid organs." (PMID 38578569, 2024).
Obesity (1 paper, 2017). Accumulation of substantial excess body fat. "Thus, the obesity-related defect in STIM2 translocation was present but less dramatic than that observed for STIM1." (PMID 29243589, 2017).
peritonitis (1 paper, 2015). Inflammation of the peritoneum (tissue that lines the abdominal wall and covers most of the organs in the abdomen). "Furthermore, STIM2-deficient animals showed decreased macrophage recruitment in the model of Thg-induced peritonitis and reduced TNFα, IL-6, and IL-1β serum levels in LPS-induced inflammation." (PMID 26417434, 2015). "Similar to STIM2-deficient mice, Stim2−/− chimeras showed no negative effect on 34-3C mAb-induced AIHA but exhibited reduced Thg-peritonitis and LPS inflammation." (PMID 26417434, 2015). "Here, we identify the closely related STIM2 as mediator of cell migration and cytokine production downstream of GPCR and TLR4 activation in macrophages and show that mice lacking STIM2 are partially resistant to inflammatory responses in peritonitis and LPS-induced inflammation." (PMID 26417434, 2015).
prostate adenocarcinoma (1 paper, 2024). "In an aged knock-in mouse prostate adenocarcinoma model, ORAI3 and STIM2 mRNA levels were significantly increased compared to ORAI1 and STIM1, and ORAI3–STIM2 interaction was detected in PC–3 cells under basal conditions." (PMID 38672434, 2024).
rectum tumor (1 paper, 2019). "However, only the TCGA dataset contained rectum tumor samples, in which the expression profiles of KCNN2, STIM2 and TRPM6 followed that of the distal tumor samples." (PMID 31010205, 2019).
Sepsis (1 paper, 2015). Sepsis is defined as life-threatening organ dysfunction caused by a dysregulated host response to infection. "Since these reactions are not largely dependent on STIM1 but are reduced in BTP2-treated mice, STIM2 may be a possible target through which BTP2 suppresses cell migration and provides protection against cytokine-mediated effects in sepsis." (PMID 26417434, 2015).
temporal lobe epilepsy (1 paper, 2020). A localization-related (focal) form of epilepsy characterized by recurrent seizures that arise from foci within the temporal lobe, most commonly from its mesial aspect. "Accordingly, the expression of both STIM1 and STIM2 is highly increased in hippocampal specimens of a patient with temporal lobe epilepsy." (PMID 32315120, 2020).
type 1 diabetes (1 paper, 2018). "In this study we showed that both in pregnancy and in type 1 diabetes the mRNAs encoding proteins forming the pore of the CRAC channels, the ORAI1-3, were up-regulated whereas the low-affinity Ca2+ sensor gene, STIM2, was down-regulated." (PMID 30543678, 2018). "Our results show that in pregnancy and type 1 diabetes ORAI1-3 are up-regulated whereas STIM1 and 2 are down-regulated in pregnancy but only STIM2 in type 1 diabetes." (PMID 30543678, 2018).
tumor (20 papers, 2013 to 2024). "These imply that STIM1 is associated with tumor growth and invasion, whereas STIM2 is mainly correlated with tumor growth." (PMID 35008759, 2021). "The STIM2 loss in tumor cells moves internal Ca2+ store concentration near to the SOCE activation threshold and promotes apoptosis resistance and cell survival." (PMID 32733237, 2020). "These imply that STIM1 is associated with both tumor growth and invasion, whereas STIM2 is mainly correlated with tumor growth." (PMID 31252656, 2019). "This is while STIM2 is mainly associated with tumour growth." (PMID 37259313, 2023). "In this sense, SOCE/STIM2 prime the glucose metabolism of T cells that competes with its neighbor tumor cells, and the abnormalities of STIM2 or its downstream will render immune suppression resulting from T dysfunction." (PMID 39272139, 2024). "Then we discuss the translation of these researches into antitumor approaches, emphasizing the potential of STIM2 as a therapeutic target for direct inhibition of tumor cells or more activation towards immune cells driving to flare TME." (PMID 39272139, 2024). "This review is an update on STIM2, aiming to rationalize the potential of STIM2 as a therapeutic target for immunomodulation, engaging immune cells to exert the utmost anti-tumor effect." (PMID 39272139, 2024). "The metabolic fitness of immune cells is pivotal for anti-tumor immunity, thus effectuating the STIM2 activity on AMPK signaling in favor of optimal immuno-environment in the anti-tumor armamentarium." (PMID 39272139, 2024). "We also outline the advancements on the underlying mechanism how STIM2 anomalies influence the function of immune cells and on the turbulent expression or/and amenably modification of STIM2 within the tumor niches." (PMID 39272139, 2024). "When STIM2 was depleted in mice, the production of TNF-α, IL-1β and IL-6 was blocked, thus dampening the tumor-infiltration associated inflammation." (PMID 39272139, 2024). "CD8+ cytotoxic T cells are the prime killers, which fight against tumor cells mainly via cytolytic granules release, cytokines secretion and FasL expression that are highly dependent on the expression and activity of STIM2." (PMID 39272139, 2024). "It is postulated but still needs further investigation if and how tumor cells with STIM2 abnormalities impacts the immune cellular activities and functions." (PMID 39272139, 2024). "The suppression of such functions counteracted anti-tumor immunity by preventing the control of melanoma and colon carcinoma cell growth and their engraftment in STIM1- and STIM2- deficient cytotoxic T cells." (PMID 34201758, 2021). "The simultaneous STIM1 and STIM2 immunostaining showed that, despite the overexpression of both isoforms in tumor tissues, STIM1 is the principle ER Ca2+-sensing molecule detected in the invasive tumor front." (PMID 35008759, 2021). "Not only the main players of SOCE, STIM1 and Orai1, but also the slightly “neglected” STIM2 and Orai3 are involved in proliferation and growth of tumor cells." (PMID 30935064, 2019). "Implantation of STIM2-SH (knockdown) cells induced significantly less tumor growth than did implantation of control cells, whereas implantation of STIM2-OE cells induced larger tumors than did control cells." (PMID 31464639, 2019). "Further work needs to clarify if the microtubule-dependent SOCE activation is context-dependent, perhaps in tumor cells expressing constitutively-activated STIM2." (PMID 31252656, 2019). "Stim1 protein was upregulated in CRC tissues as compared to adjacent non-tumor tissues, whereas Stim2 transcripts were over-expressed in a well annotated cohort of CRC patients treated with adjuvant 5-FU chemotherapy." (PMID 30123430, 2018). "Taken together, our results show for the first time that activation of CRAC channels by STIM1 and STIM2 proteins is essential for tumour immunosurveillance by CD8+ T cells." (PMID 23922331, 2013).
tumor (continued). "Of note, this paper provides some theories about the individual importance of STIM1 and STIM2 in cytotoxic T-cell function against tumour cells." (PMID 24000152, 2013). "We found that SOCE in T cells curtails the growth of tumour allografts and that STIM1 and STIM2 deficient CTLs fail to prevent tumour cell engraftment." (PMID 23922331, 2013). "STIM1 and STIM2 are dispensable for the priming, expansion and homing of tumour antigen-specific CTLs." (PMID 23922331, 2013). "A study involving immunostaining of overexpressed STIM1 and STIM2 in human cervical cancer revealed that STIM1 is the main endoplasmic reticulum Ca2+-sensing molecule found in the invasive tumour front, indicating that STIM1 plays a role in both tumour growth and invasion." (PMID 37259313, 2023). "Moreover, STIM2, found abundantly in colon cancer cells, can elicit an anti-apoptotic effect on such tumor cells." (PMID 34572262, 2021). "Moreover, the expression of TRPC1, ORAI1, ORAI2, ORAI3 and STIM1 was increased in tumor cells in contrary to STIM2 protein which was found to be depleted." (PMID 31010205, 2019). "The sustained Ca2+ release required for the nuclear translocation of NFAT and its subsequent regulation of FasL expression lends support to the theory that intact SOCE as regulated by STIM1, STIM2, Orai1 can have transcriptional effects that affect the function of cytotoxic T cells against tumours." (PMID 24000152, 2013). "In CRC, STIM2 loss leads to the increase of SERCA2-dependent ER Ca2+, and then activates c-Myc and the PERK/ATF4 branch of ER stress facilitating the increased protein translation and transcriptional and metabolic rewiring which support increased tumor size, invasion, and metastasis." (PMID 39272139, 2024). "Recently, the novel structures or isoforms and the explicable functions of STIM2 have been unraveled on Ca2+ homeostasis, adaption to metabolism reprogram, as well as its cytosol accountable interface modulated by the soluble factors within the tumor microenvironment (TME)." (PMID 39272139, 2024). "Therefore, the use of the STIM1/STIM2 ratio as a marker of tumor aggressiveness might be promising and worth further evaluated." (PMID 31252656, 2019). "Further studies would contribute to the understandings of the clinical implications of such patterns of STIM1/STIM2 expression and the grades of STIM1 distribution in the invasive tumor front." (PMID 31252656, 2019). "Results from the simultaneous immunostaining of STIM1 and STIM2 showed that, despite the overexpression of both isoforms in tumor tissues, STIM1 is the principle ER Ca2+-sensing molecule detected in the invasive tumor front." (PMID 31252656, 2019). "STIM2 mediated the NFAT1 nuclear translocation for promoting the expression of its downstream targets including FasL, IFN-γ, interleukin (IL)-2, IL-17 expression that interprets and accentuates the key role of STIM2 in the T cells on tumor cells-killing." (PMID 39272139, 2024). "Mechanistically, STIM1 and STIM2 are crucial for the cytolytic effector functions of CTLs, especially the production of IFN-γ and TNF-α, the release of perforin-containing cytolytic granules, the induction of FasL, and thus tumor cell killing." (PMID 31252656, 2019). "It was found that mice lacking STIM1 and STIM2 in CTLs fail to adequately control tumor cell engraftment and growth in vivo." (PMID 31252656, 2019). "In comparison, reduction of Stim2 in normal mucosal cells reduced SOCE and Ca2+ store content and promoted apoptosis resistance, suggesting a role for downregulated Stim2 expression in tumor cell survival." (PMID 29783744, 2018). "Accordingly, CD8+ T cells lacking STIM1 and STIM2 failed to kill tumour cells both in vitro and in vivo." (PMID 23922331, 2013).
tumor (continued). "In addition, loss of STIM2 affected the ability of T cells to maintain NFAT concentrations in the nucleus, implicating that even STIM2 mutations could potentially impact transcriptional processes in cytotoxic T cells that are important for their activity against tumour cells." (PMID 24000152, 2013). "SOCE in cytotoxic CD8+ T cells was essential to control the engraftment of tumour cells as only wild-type CD8+ T cells but not those lacking STIM1 and STIM2 prevented tumour growth." (PMID 23922331, 2013). "Since the expansion and tumour infiltration of CTLs is independent of STIM1 and STIM2, we speculated that cytolytic effector functions of tumour-specific CD8+ T cells may require SOCE." (PMID 23922331, 2013). "It is noteworthy that, while STIM2 gene expression levels are increased in CRC cells, STIM2 protein is practically absent in tumor cells, leading to the partial depletion of calcium stores." (PMID 32733237, 2020). "In spite that STIM2 protein expression does not change with DFMO, the ratio STIM1/STIM2 is indeed reduced by DFMO treatment consistently with reversal of the tumor phenotype." (PMID 30642111, 2019).
cancer (19 papers, 2008 to 2026). A tumor composed of atypical neoplastic, often pleomorphic cells that invade other tissues. "This is due to either altered expression of CRAC channel proteins, specifically, STIM1/STIM2, Orai1, and Orai3 in cancer cells compared with healthy cells or mutations in STIM1 or Orai1 proteins." (PMID 36612099, 2022). "Aberrant expression of STIM1 and STIM2 proteins has been associated with human cancer but their direct role in tumorigenic events has yet to be established." (PMID 18950512, 2008). "Store-operated calcium entry (SOCE), mediated by ORAI1-3 calcium channels and stromal interaction molecules STIM1 and STIM2, is increasingly recognized as a regulator of cancer progression." (PMID 41801973, 2026). "Previous studies have shown that the endoplasmic reticulum (ER) Ca2+ sensors, stromal interaction molecules STIM1 and STIM2, are key regulators of cancer cell migration." (PMID 40719699, 2025). "On the other hand, CRC cancer cells exhibit downregulated expression of STIM2 leading to a greater STIM1:STIM2 ratio that supports enhanced SOCE." (PMID 38514909, 2024). "In some cancer types, Orai3 and/or STIM2 expression exerts pro-proliferative effects by influencing the cell cycle via various signaling cascades." (PMID 36612099, 2022). "In the following, we will focus on STIM1 and STIM2, because only these two isoforms have been described as playing a role in cancer." (PMID 36612099, 2022). "Orai3 is a calcium channel activated by Stim1 or Stim2,9 but in further studies, Orai3 interacted with Orai1 to form a heteromer was recognized in cancer cells for proliferation and decreased apoptosis." (PMID 36128650, 2022). "For example, several cancers have been associated with upregulated expression of STIM1, STIM2, or Orai1 and increased SOCE." (PMID 29783744, 2018). "Specifically, the dysregulation of distinct molecular components of SOCE, especially the STIM1 and Orai1 proteins and their homologues STIM2, Orai2, and Orai3, plays important roles in the pathophysiology of different types of cancer." (PMID 29951353, 2017). "Additionally, Orai2 in the hematologic tumor type, acute myeloid leukemia cells (AMLC), and STIM2 in melanoma manifest the invasive phenotype of the respective cancer types." (PMID 36612099, 2022). "The skin/cancer-related genes in the most significant focally amplified regions worth mentioning are STIM2 (chr4p15.2; q=0.16; occurring in 2 samples), KLRB1/CD161 (chr12p13.31; q=0.007; occurring in 2 samples), and SPTLC3 (chr20p12.1 q=0.23; occurring in 2 samples)." (PMID 34900699, 2021). "The observation of significant higher expression of STIM2 in ESCC cell lines than that in HET-1A cells implies that STIM2 may play an important role in regulation of Orai1 channel activity and overall intracellular Ca2+ signaling in this type of cancer." (PMID 24797725, 2014). "In particular, STIM2 or Orai3 may function as a therapeutic target for selective cancer therapy." (PMID 36612099, 2022). "It applauses the possibility that STIM2 may replace STIM1 to couple with Orai1 in cancer cells." (PMID 24797725, 2014). "We show that while deletion of either STIM1 or STIM2 inhibits the migration of cancer cells, deletion of both STIM isoforms (dKO) does not." (PMID 40719699, 2025). "Lack of STIM2 role in proliferation has been recently described in other cancer cell lines." (PMID 33076541, 2020). "Six of the 10 remaining genes, despite not being listed, were genes for which literature search supported undeniable oncogenic properties (STIM2, ARHGAP24, KLF12, KMT2C, CCDC88C and DOCK11), and 4 genes were—to our knowledge—not previously reported in cancer, yet may include new candidate drivers." (PMID 28534499, 2017).
infection (2 papers, 2021 to 2025). The state of being infected such as from the introduction of a foreign agent such as serum, vaccine, antigenic substance or organism. "Contrary to SKAP1 gene the methylation changes associated with STIM2 gene appear to take part in infection progression because methylation levels at CpG sites associated with this gene differed between infection stages." (PMID 40537863, 2025). "Importantly, we were able to confirm key role of methylation changes at enhancers during infection progression with detailed analysis of methylation changes that we linked to STIM2 gene which is one of the key genes involved in infection progression and general host response to virus." (PMID 40537863, 2025). "To verify the hypothesis that excessive SOCE in HD76 neurons depends on STIM2, we knocked down its expression in HD76 by lentiviral infection of shRNA against STIM2." (PMID 33604336, 2021).
genetic disorders (1 paper, 2022). "Although STIM2 is commonly regarded as the primary regulator of basal Ca2+ entry, constitutive activation of STIM1 enhances background Ca2+ influx and, thereby, increases resting [Ca2+]i and/or ER Ca2+ levels in several genetic disorders." (PMID 36371290, 2022).
neurological diseases (1 paper, 2023). "The dysfunction of STIM proteins, particularly STIM2, has also been detected in various neuronal cell and animal models of neurological diseases." (PMID 37989792, 2023).
STIM2 also shares sentences with these, for which no sentence is quoted: breast tumor (2 papers); triple-negative breast carcinoma (2); adenocarcinoma (1); bladder cancer (1); developmental delay (1); eosinophilia (1); esophageal tumor (1); hypogonadism (1); inflammation (1); Lymphadenopathy (1); metastatic melanoma (1); microcephaly (1); migraine (1); multiple sclerosis (1); skeletal myopathies (1); Varicose veins (1); viral infection (1).